NLRP3 (NLR family pyrin domain containing 3)
Diseases named in the same sentence as NLRP3 in open-access papers (continued):
Sharing a sentence is not in itself a finding about the gene and the disease.
subarachnoid hemorrhage (42 papers, 2017 to 2026). A serious neurological disorder characterized by intracranial hemorrhage into the subarachnoid space. "Mechanistically, phosphodiesterase 4 triggered the nuclear factor kappa-B pathway, and simultaneously caused lysosomal and mitochondrial dysfunction after subarachnoid hemorrhage, which promoted NLRP3 inflammasome activation and induced neuronal pyroptosis." (PMID 40537006, 2025). "This is in line with a recent finding that dexmedetomidine attenuates subarachnoid hemorrhage-associated brain injury by inhibiting the NLRP3 inflammasome pathway." (PMID 30778043, 2019). "Together, the results indicate that phosphodiesterase 4 regulates NLRP3-mediated neuronal pyroptosis in early brain injury after subarachnoid hemorrhage." (PMID 40537006, 2025). "Its activation suppresses the NLRP3 inflammasome via autophagy induction, leading to reduced neuroinflammation and improved neurological recovery following subarachnoid hemorrhage." (PMID 40428819, 2025). "SRT1720, an agonist of Sirt1, can improve cell viability, promote M2 microglia polarization, suppress inflammatory response and inhibit oxidative damage via modulation of ROS-mediated NLRP3 inflammasome signaling after subarachnoid hemorrhage." (PMID 36725745, 2023). "For instance, MLT was also demonstrated to protect against brain damage induced by subarachnoid hemorrhage (SAH) via the suppression of NLRP3 inflammasome-related components, including ASC, cleaved Casp-1, IL-1β, and IL-669,70." (PMID 36747075, 2023). "The nucleotide-binding oligomerization domain (NOD)-like receptor family pyrin domain containing 3 (NLRP3) inflammasome-mediated immuno-inflammatory response plays a critical role in exacerbating early brain injury (EBI) after subarachnoid hemorrhage (SAH)." (PMID 37564636, 2023). "Current studies have shown that a variety of inflammasomes are involved in the process of neuronal cell pyroptosis, such as AIM2, NLRP1, and NLRP3, after subarachnoid hemorrhage, among which NLRP3 is the best studied." (PMID 38044382, 2023). "In experimental subarachnoid hemorrhage, resveratrol decreased early brain injury, neuroinflammation and microglia activation through inhibition of NLRP3 inflammasome activation or TLR4 pathway." (PMID 36836502, 2023). "In this study, we defined the role of NLRP3 in both the acute and delayed phases following subarachnoid hemorrhage (SAH)." (PMID 34284798, 2021). "It was also suggested in our previous study that PTE can attenuate early brain injury following subarachnoid hemorrhage, possibly via the inhibition of NLRP3 inflammasome and Nox2-related oxidative stress." (PMID 31681297, 2019). "The NLRP3 inflammasome is activated in the early period following subarachnoid hemorrhage(SAH), resulting in inflammatory responses." (PMID 28546552, 2017). "Similarly, a recent study found that the With No lysine (K) kinase 1 can alleviate neurological dysfunction following subarachnoid hemorrhage by inhibiting P2X7R- related NLRP3 inflammasome activation." (PMID 41383474, 2025). "Additionally, TGR5 activation can mitigate NLRP3 inflammasome-mediated neuroinflammation following subarachnoid hemorrhage." (PMID 39328272, 2024). "Furthermore, fluoxetine mitigates NLRP3 inflammasome and caspase-1 activation through autophagy activation after subarachnoid hemorrhage (SAH) to treat early brain injury." (PMID 35810159, 2022). "Finally, in a mouse model of subarachnoid hemorrhage melatonin blunted NLRP3 activation reducing the levels of ROS and other oxidants, improving neuron survival." (PMID 28769794, 2017). "Furthermore, NLRP3 inflammasome activation was showed to be associated with the upregulation of apoptotic signaling pathway in various inflammatory diseases and melatonin attenuated subarachnoid hemorrhage-induced BBB damage via attenuating the expressions of NLRP3." (PMID 28596733, 2017).
subarachnoid hemorrhage (continued). "By suppressing the activation of caspase-1 and preventing the assembly of the NLRP3 inflammasome, inhibiting P2X7R can reduce the production of IL-1β/IL-18 and lessen early brain damage in the subarachnoid hemorrhage model." (PMID 41383474, 2025). "In subarachnoid hemorrhage injury, SIRT1 facilitates M2 microglial polarization by suppressing ROS-mediated NLRP3 inflammasome activation, thus alleviates early brain injury." (PMID 38745316, 2024). "Neuroinflammation plays a key role in early brain injury (EBI) of subarachnoid hemorrhage (SAH), and NLRP3 inflammasome plays an important role in the development of neuroinflammation after SAH, but the mechanism of NLRP3 inflammasome activation after SAH is still unclear." (PMID 38180747, 2024). "In the context of subarachnoid hemorrhage in mice, inhibition of HSP90 by 17-AAG (17-allylamino-17-demethoxygeldanamycin) was shown to inhibit NLRP3 inflammasome activation, whereas the transfection of recombinant HSP90 (rHSP90) increases NLRP3 activation and abolishes the effect of 17-AAG." (PMID 31547225, 2019). "It has been reported that NLRP3 mediates many kinds of nervous system injuries after ICH, subarachnoid hemorrhage or traumatic brain injury, but there are no studies about the NLRP3 inflammasome in hydrocephalus." (PMID 35729645, 2022).
familial Mediterranean fever (41 papers, 2008 to 2025). Familial Mediterranean fever (FMF) is an autoinflammatory disorder characterized by recurrent short episodes of fever and serositis resulting in pain in the abdomen, chest, joints and muscles. "Unexpectedly, however, GSDMD-independent secondary necrosis does not appear to be important in models of autoinflammatory diseases because Gsdmd deficiency rescues mice expressing mutant NLRP3 or Pyrin, linked to neonatal-onset multisystem inflammatory disease and familial Mediterranean fever." (PMID 32345661, 2020). "For many years, Nlrp3 inflammasomes’ role was associated with several pathologies, such as dominantly inherited auto-inflammatory diseases known as a cryopyrin-associated periodic syndrome or familial Mediterranean fever." (PMID 33584673, 2020). "In familial Mediterranean fever, pyrin has been shown to function also as an autophagy receptor that targets the inflammasome components NLRP3, NLRP1, and caspase-1 for degradation." (PMID 38593810, 2024). "Among others, mutations affecting the MEFV gene, which is responsible for familial Mediterranean fever (FMF) and encodes the protein pyrin, an essential regulator of the NLRP3 inflammasome, have been associated to an increased frequency of SpA, disregarding the HLA-B27 haplotype." (PMID 37324154, 2023). "Activation of the NLRP3 inflammasome is highly involved in the etiology and pathology of familial Mediterranean fever (FMF) and CAPS." (PMID 33143375, 2020). "Familial Mediterranean fever is an IL-1β dependent auto-inflammatory disease and is related to dysregulation of nod-like receptor family pyrin domain-containing 3 inflammasome (NLRP3)." (PMID 25887962, 2015). "P3 presented with sacroiliitis which has been a well-established complication of another closely related autoinflammatory disease - familial Mediterranean fever but has not been reported in NLRP3-associated AID." (PMID 40757135, 2025). "The expansion of research in this area has uncovered PYRIN and NLRP3 inflammasomes and related autoinflammatory diseases such as familial Mediterranean fever (FMF) and hypothermic inflammation-related periodic fever syndrome (CACFS)." (PMID 34276697, 2021). "The four most common monogenic AIDs are: NLRP3-associated autoinflammatory disease (NLRP3-AID), familial Mediterranean fever (FMF), mevalonate kinase deficiency (MKD), and tumor necrosis factor receptor-associated periodic fever syndrome (TRAPS)." (PMID 33530412, 2021). "Autoinflammatory mechanisms are primarily driven by the activation of the inflammasome, particularly the NLRP3 inflammasome, leading to the production of interleukin-1 (IL-1) and similarities with autoinflammatory condition such as Familial Mediterranean Fever (FMF)." (PMID 40665038, 2025).
type 1 diabetes (41 papers, 2012 to 2025). "Low NLRP3 expression was associated with leishmania infection, graft versus host disease, type I diabetes mellitus, Nod-like receptor signaling pathway, and intestinal immune network for IgA production." (PMID 38690269, 2024). "Pattern recognition receptors (PRRs), such as Nod2, Nlrp3, Tlr2, Trl4, and Tlr9, are directly involved in type 1 diabetes (T1D) susceptibility." (PMID 32295112, 2020). "One of the most important findings of this study is the association between NLRP3 and vascular dysfunction in type 1 diabetes." (PMID 32009974, 2019). "In addition, NLRP3 inflammasome activation by mDNA plays a major role in pathogenic cellular immune responses mediated by T lymphocytes during type 1 diabetes development, contributing to damage of insulin-producing β cells, as we recently demonstrated." (PMID 32009974, 2019). "However, in the Chinese Han population, whether NLRP3 polymorphisms are associated with type 1 diabetes (T1D) is unclear." (PMID 35528000, 2022). "The pathogenic role of NLRP3 has been demonstrated in systemic lupus erythematosus, inflammatory bowel disease, and type 1 diabetes mellitus(T1DM)." (PMID 35833125, 2022). "Studies have shown that NLRP1 and NLRP3 inflammasomes exert a synergistic effect and have a protective function on the body in the early stage of type 1 diabetes." (PMID 36993972, 2023). "In the heart of a type 1 diabetes mouse model, cathepsin B is released from lysosomes, which activates NLRP3, triggering pyroptosis." (PMID 36742461, 2023). "Wild-type (WT) and Nlrp3 knockout (KO) C57BL/6 mice were used to establish a type I diabetes model by intraperitoneal injection of streptozotocin." (PMID 35002527, 2022). "Numerous studies have shown that the NLRP3 inflammasome is involved in the pathogenesis and progression of both type 1 diabetes (T1DM) and type 2 diabetes (T2DM)." (PMID 34948026, 2021). "Although inflammation plays a key role in type 1 diabetes development, few experimental and clinical studies have evaluated the involvement of NLRP3 activation on vascular inflammatory processes and its repercussion on endothelial function." (PMID 32009974, 2019). "In the present study, mesenteric arteries from Nlrp3–/– mice with type 1 diabetes displayed decreased expression of Nox4 and reduced ROS levels." (PMID 32009974, 2019). "Bacteroides are enriched in women with type 1 diabetes at 3 months of pregnancy and are part of the LPS bacterial population and may be involved in regulating the NLRP3 inflammasome to control inflammation." (PMID 37024673, 2023). "Administration of pharmacological FoxO1 inhibitor ameliorated type 1 diabetes‐induced vascular remodelling through decreasing the expression of pro‐inflammatory factors, NLRP3 inflammasome activation, adhesion factors, MMPs and apoptosis, reversing the SMCs phenotypic switching." (PMID 33108705, 2020). "Similarly, CTSB can induce NLRP3-mediated pyroptosis in the heart of type 1 diabetic mouse." (PMID 36742461, 2023). "NLRP3 inflammasome activation reportedly mediates podocyte damage in db/db type 2 diabetic mice and STZ-induced type 1 diabetic mice." (PMID 37373116, 2023). "Inhibition of P2X7R decreases renal inflammation and improves functional parameters in the Streptozotocin mouse model of type 1 diabetes, whilst here, co-incubation of TGFβ1-treated primary hPTECs with a P2X7R antagonist (A438079) prevented NLRP3 activation." (PMID 37770948, 2023). "Further, some authors reported that intrarenal NLRP3/Caspase 1 inflammasome activation was present in both the db/db mouse and the murine STZ-induced type 1 diabetes model." (PMID 31540220, 2019). "Alternatively, NLRP3 has been shown to play roles in cellula processes not directly related to immunity, including type 1 diabetes, mitochondrial function andendosomal transport, which are common targets of Dot/Icm effectors." (PMID 40953119, 2025).
type 1 diabetes (continued). "Although a correlation between polymorphisms of NOD-like receptor family-pyrin domain containing 3 (NLRP3) and predisposition to type 1 diabetes (T1D) has been identified, the potential function and activation of the NLRP3 inflammasome in T1D have not been clarified." (PMID 28289409, 2017).
osteoporosis (40 papers, 2019 to 2026). A condition of reduced bone mass, with decreased cortical thickness and a decrease in the number and size of the trabeculae of cancellous bone (but normal chemical composition), resulting in increased fracture incidence. "Snouwaert et.al reported that an NLRP3 mutation induced inflammation and caused osteoporosis and arthropathy in humanized mice." (PMID 38994035, 2024). "Accumulative evidence indicates the pathogenic role of NLRP3 inflammasome signaling in RA and its comorbidities, including atherosclerotic cardiovascular disease, osteoporosis, and interstitial lung diseases." (PMID 38203796, 2024). "Occupation of NLRP3 inflammasome can accelerate bone resorption, promote osteoclast differentiation and aggravate inflammation, which increase the risk of osteoporosis." (PMID 36941678, 2023). "NLRP3 inflammasome plays an important role in the development of osteoporosis by reducing differentiation, causing dysfunction of the osteoblasts, and accelerating osteoclasts, thus promoting bone resorption and impaired bone formation." (PMID 37958752, 2023). "The study in postmenopausal women with osteoporosis demonstrated that single-nucleotide variants in NLRP3 inflammasome pathway genes activating pro-inflammatory cytokines IL-1β and IL-18 production are associated with osteoporosis severity." (PMID 37958752, 2023). "In conclusion, NLRP3 inflammasome overall not only accelerates bone resorption, but also inhibits bone formation, thus increasing the risk of osteoporosis." (PMID 34646239, 2021). "In fact, mice with the humanized NLRP3 locus and disease-associated mutations develop thinner and radiolucency cortices, consistent with osteoporosis." (PMID 34177950, 2021). "Patients presenting genetic mutations that lead to chronic NLRP3 activation show a higher incidence of osteoporosis." (PMID 32604771, 2020). "A recent study found that melatonin ameliorates estrogen deficiency-induced osteoporosis by suppressing the activation of the NLRP3 inflammasome via mediating the Wnt pathway." (PMID 31886199, 2019). "High expression levels of NLRP3 inflammasome and IL-1β deteriorate osteoporosis under estrogen deficiency by inhibiting osteogenic differentiation." (PMID 31146750, 2019). "MSC-EVs ameliorate osteoporosis by inhibiting NOD-like receptor thermal protein domain associated protein 3 (NLRP3) inflammasome activation, as the negative regulation of NLRP3 inflammasome activation inhibits IL-1β and IL-18 secretion in osteoclasts, promoting recovery from bone loss." (PMID 38697996, 2024). "Furthermore, uncontrolled activation of NLRP3 is associated with osteopenia, a preliminary stage of osteoporosis." (PMID 35052653, 2022). "The activated NOD-like receptor family pyrin domain-containing protein 3 (NLRP3) inflammasome is an important player in aging-related chronic diseases like osteoporosis, especially because of the causal caspase-1 activation and its correlation to adipose accumulation in bone tissues." (PMID 35308164, 2021). "Moreover, the degradation products of bone turnover act as stimulants of NLRP3, and estrogen deficiency-induced osteoporosis is less severe in NLRP3-deficient mice." (PMID 34202842, 2021). "NLRP3 is considered essential in many bacterial infections caused by osteoporosis." (PMID 33488513, 2020). "Exos‐mediated regulation of the NLRP3 inflammasome in osteoporosis: Mechanisms and functional implications." (PMID 40853781, 2025). "The clinical application of small molecule inhibitors regulating Nlrp3 inflammasome in osteoporosis." (PMID 40853781, 2025). "Study on the mechanism and function of clinical drugs regulating Nlrp3 inflammasome in osteoporosis." (PMID 40853781, 2025). "Osteoporosis has a destructive effect on bone tissue through different mechanisms: nuclear factor-κβ ligand and NLRP3/Caspase-1/IL-1β cascade." (PMID 38759999, 2024).
osteoporosis (continued). "Numerous studies examined the relevance of NLRP3 to osteoporosis, indicating that its inhibition can mitigate osteoporosis, cell death, and inflammation." (PMID 39457537, 2024). "Irisin inhibited NLRP3-mediated pyroptosis in BMSCs and alleviated streptozotocin-induced osteoporosis." (PMID 38895114, 2024). "Estrogen deficiency curtailed osteogenic differentiation of BMSCs by promoting the Capsase-1/GSDMD/IL-18 and IL-1β pyroptosis pathways, culminating in osteoporosis, while NLRP3 knockdown fostered bone formation." (PMID 38895114, 2024). "When rats with OA were treated with anti-inflammatory and anti-osteoporosis drugs, caspase-1-dependent pyroptosis induced by the NLRP3 inflammasome was attenuated, suggesting the pernicious role of pyroptosis in OA." (PMID 38934781, 2024). "In humans, IL-18, one of the downstream signaling events of the NLRP3 inflammasome, is elevated in patients with osteoporosis, and therapeutics targeting the NLRP3 inflammasome are of interest for osteoporosis treatment." (PMID 38221578, 2024). "CYLD mitigates NLRP3 inflammasome-triggered pyroptosis in osteoporosis through its deubiquitination of WNK1." (PMID 38561786, 2024). "Melatonin alleviated osteoporosis by suppressing NLRP3 activation through the Wnt/β-catenin pathway." (PMID 38895114, 2024). "Emerging evidence suggests that the NLRP3 inflammasome plays a vital role in bone formation and the pathogenesis of osteoporosis by affecting the differentiation of osteoblasts and osteoclasts through autocrine and paracrine manners." (PMID 37621124, 2023). "Several studies on treatment approaches aimed to modulate NLRP3 inflammasome activity and inflammatory cytokines production reported beneficial effects of therapy on bone metabolism and osteoporosis development." (PMID 37958752, 2023). "The NLRP3 inflammasome, which is a new target for the prevention and control of osteoporosis, can promote bone resorption and inhibit osteogenesis." (PMID 36590590, 2022). "Taken together, these studies indicate that the NLRP3 inflammasome plays a dual role in bone metabolism, and its abnormal activation affects the development of osteoporosis." (PMID 35628185, 2022). "There is increasing evidence implicating that NLRP3 inflammasome is a potential target for therapy because of its involvement in several diseases, such as osteoporosis, osteoarthritis, and rheumatoid arthritis." (PMID 35872849, 2022). "Aging, estrogen deficiency, or hyperparathyroidism provide a chronic inflammatory microenvironment and enhance NLRP3 activation, which can further lead to bone resorption and genesis of osteoporosis." (PMID 35052653, 2022). "Regulating the NLRP3 inflammasome would be a promising therapeutic strategy to prevent and control osteoporosis." (PMID 35628185, 2022). "We summarize the related research and demonstrate that the NLRP3 inflammasome plays a vital role in the pathogenesis of osteoporosis by affecting the differentiation of osteoblasts and osteoclasts." (PMID 34646239, 2021). "Inflammaging and NLRP3 are involved in other age-related diseases with high prevalence, such as arthritis, osteoporosis, and cardiovascular diseases." (PMID 32604771, 2020). "NLRP3 is capable of promoting progressive and debilitating arthritis characterized by granulocytic infiltration, elevated cytokines, bone erosion, and osteoporosis in humanized mice." (PMID 33488513, 2020). "NLRP3 directly inhibits osteogenesis by affecting osteoblasts and plays a core role in osteoporosis induced by inflammation." (PMID 33488513, 2020). "Additionally, NLRP3 inflammasome was activated as inflammatory promoters in patients with osteoporosis which was significantly suppressed by melatonin use in patients with postmenopausal osteoporosis." (PMID 34938374, 2021).